TERT (telomerase reverse transcriptase)
Diseases named in the same sentence as TERT in open-access papers (continued):
Sharing a sentence is not in itself a finding about the gene and the disease.
oral squamous cell carcinoma (13 papers, 2018 to 2025). "The telomerase reverse transcriptase (TERT) promoter mutations have been linked to the prognosis and survival of several cancers; however, it is still debatable in case of oral squamous cell carcinoma." (PMID 40307280, 2025). "The telomerase reverse transcriptase (TERT) gene has been previously shown to be a more common mutation in oral cavity squamous cell carcinoma when compared to other types of head and neck malignancies." (PMID 39831137, 2025). "Further exploration of HNC tumors revealed that oral cavity squamous cell carcinoma (OSCC) tumors (44%, n = 85/192) were associated with higher TERT promoter mutations vs. other HNC subtypes (17%, n = 98/590) (OR = 3.98; 95%CI, 2.74-5.79; Q = .03)." (PMID 37462445, 2024). "The aim of this systematic review and meta-analysis was to evaluate the current evidence on the prognostic and clinicopathological significance value of telomerase reverse transcriptase (TERT) upregulation in patients with oral squamous cell carcinoma (OSCC)." (PMID 35954336, 2022). "Distribution of 144 patients with oral cavity squamous cell carcinoma (OCSCC) according to socio-demographic and clinical characteristics, by TERT promoter mutational status." (PMID 34858860, 2021). "Though previously associated with human papilloma virus (HPV), another study found that ‐124G>A and ‐146G>A mutations in the TERT gene significantly affected the development of oral squamous cell carcinoma regardless of HPV‐status." (PMID 39831137, 2025). "Telomerase activity contributes to cell immortalization by avoiding telomere shortening at each cell division; indeed, its catalytic subunit telomerase reverse transcriptase (TERT) is overexpressed in many tumors, including human oral squamous cell carcinoma (hOSCC)." (PMID 32292795, 2020). "Indeed, TERT is expressed in most cancers, including human oral squamous cell carcinoma (hOSCC)." (PMID 32292795, 2020). "This is the first systematic review and meta-analysis, based on 21 studies and 1698 oral squamous cell carcinoma (OSCC) patients, demonstrating that TERT protein overexpression behaves as a prognostic biomarker, significantly associated with poor survival in oral cancer." (PMID 35954336, 2022).
aplastic anemia (12 papers, 2008 to 2022). Anemia resulting from bone marrow failure (aplastic or hypoplastic bone marrow). "Collectively, these findings showed that telomere attrition, which causes BM dysfunction and aplastic anemia in patients, can be effectively treated by TERT gene transfer." (PMID 31035374, 2019). "The V1090M variant, located in the C-terminal of TERT, was described in a 64-year-old Hispanic patient with severe aplastic anemia and short telomeres (allele frequency of 0.005)." (PMID 28813500, 2017). "In summary, we report a novel hereditary T1129P TERT mutation that leads to DKC with aplastic anemia that can be attributed to a severe reduction and functional impairment of CD34+ hematopoietic stem cells." (PMID 26546739, 2015). "It still needs to be elucidated how the T1129P TERT mutation exerts its effect causing aplastic anemia in affected patients." (PMID 26546739, 2015). "Our data argue against a therapeutic use of mTOR inhibitors to treat aplastic anemia in DKC patients with TERT mutations." (PMID 26546739, 2015). "Here we find aplastic anemia in 2 TERT mutation carriers, but isolated anemia in 18 individuals." (PMID 20502709, 2010). "Telomerase reverse transcriptase (TERT), the protein component of telomerase complex is not only involved in aging-related disorders and cancer, but also in RDs, such as aplastic anemia and dyskeratosis congenital." (PMID 34026829, 2021).
adenoma (11 papers, 2014 to 2023). A neoplasm arising from the epithelium. "Two additional false positive results were due to TERT promoter mutations that occurred in benign adenomas." (PMID 32767735, 2020). "Telomerase is often reactivated by TERT upregulation, which gives tumor cells their immortal quality, and this is thought to be a key step in the adenoma-carcinoma transition in human tumorigenesis." (PMID 27627813, 2016). "Two (of 5) borderline tumors showed amplifications and no TERT alterations were identified in 7 adenomas." (PMID 34549366, 2022). "Our adenomas were probably not advanced enough to display significantly upregulated TERT expression (all were larger than 10 mm, but most were characterized by low-level dysplasia)." (PMID 24472434, 2014). "As for TERT, the fifth hub in this network, its expression in our adenomas was not significantly different from that in normal mucosa." (PMID 24472434, 2014).
endometrial cancer (11 papers, 2010 to 2024). Primary or metastatic malignant neoplasm involving the endometrium (mucous membrane that lines the endometrial cavity). "Contrary to that, renal cell carcinomas showed only low numbers of TERT mutations (~10%), whereas more than 1000 endometrial carcinomas are rarely characterized by TERT alterations (<5%)." (PMID 34200508, 2021). "Association studies of candidate gene strategies also reported that SNPs in TERT were associated with serous ovarian, breast, and endometrial cancers." (PMID 26621837, 2016). "We performed high-density genotyping and genotype imputation for variants in the 5p15 TERT–CLPTM1L region to examine genetic associations with endometrial cancer risk." (PMID 25487306, 2015). "Further, a role for TERT is indicated by eQTL analyses, in that endometrial cancer risk-associated SNPs were associated with expression of TERT in endometrial tumour tissue." (PMID 25487306, 2015). "It is unclear how the loss of function of LPCAT1, TERT or SLC6A3 might contribute to endometrial cancer risk." (PMID 39495297, 2024). "To evaluate the role of genetic variants at the TERT–CLPTM1L region in endometrial cancer risk, we carried out comprehensive fine-mapping analyses of genotyped and imputed SNPs using a custom Illumina iSelect array which includes dense SNP coverage of this region." (PMID 25487306, 2015). "In the current study, we used the iCOGS array and genotype imputation to investigate whether variants in the TERT–CLPTM1L candidate region are associated with the risk of endometrial cancer in populations of European descent." (PMID 25487306, 2015). "Two of the endometrial cancer risk SNPs identified in this study are in or near the TERT gene." (PMID 25487306, 2015). "Although not commonly observed in TCs, SDHA amplifications were recently observed in endometrial carcinomas (ECs), and was also found to be co-amplified with TERT in 61% of TERT amplified ECs." (PMID 39030377, 2024). "To identify possible mechanistic associations between TERT, CLPTM1L and endometrial cancer, we searched for information on endometrial gene expression and somatic variation in publically available datasets." (PMID 25487306, 2015). "We next sought to identify the downstream target of HER-2 expression using various endometrial cancer cell lines or immortalised endometrial epithelial cells (EM-E6/E7/TERT)." (PMID 20664599, 2010). "Using TCGA RNASeq data, we found significantly increased expression of both TERT and CLPTM1L in endometrial cancer tissue compared with normal tissue (TERTP = 1.5 × 10−18, CLPTM1LP = 1.5 × 10−19)." (PMID 25487306, 2015). "First, a ‘global’ test using the admixture maximum likelihood method (AML) against the null hypothesis that none of the genotyped SNPs within the TERT–CLPTM1L region are associated with endometrial cancer provided significant evidence that at least one SNP is associated (P = 0.0001)." (PMID 25487306, 2015). "Several studies have reported associations between multiple cancer types and single-nucleotide polymorphisms (SNPs) on chromosome 5p15, which harbours TERT and CLPTM1L, but no such association has been reported with endometrial cancer." (PMID 25487306, 2015).
familial melanoma (11 papers, 2017 to 2025). Familial melanoma (FM) is a rare inherited form of melanoma characterized by development of histologically confirmed melanoma in two first degrees relatives or more relatives in an affected family. "While PVs have also been detected in several other genes, including CDK4, BAP1, ATM, MITF and multiple telomere stability genes TERT, POT1, ACD, and TERF21P, about half of the cases of familial melanoma remain unexplained." (PMID 40072281, 2025).
liver disease (11 papers, 2009 to 2025). "The prevalence of TERT promoter mutations was significantly different according to the underlying liver disease, with the highest frequency in HCV-related HCC (44%) followed by non-viral (38%) and HBV-related HCC (23%)." (PMID 33946181, 2021). "This is consistent with a recent report of a wide spectrum of familial liver disease in kindreds with telomerase mutations, including two TERT mutation families." (PMID 20502709, 2010). "The prevalence of TERT promoter mutations differed according to the etiology of liver disease." (PMID 33946181, 2021). "The most frequent mechanism by which HBV infection leads to TERT overexpression is related to insertional mutagenesis by the virus itself rather than promoter mutations or gene amplification, which is seen in other liver diseases including HCV infection." (PMID 28947783, 2017). "Considering the well-known fact that a background liver functional reservoir is the important determinant of prognosis of u-HCC patients treated with pharmacotherapy, the presence of a TERT mutation may reflect more advanced background liver disease and be associated with shorter OS." (PMID 35884434, 2022). "TERT promoter mutations (C228T and C250T) and miR-122 expression were assessed in the plasma samples from 249 patients with HBV-related liver diseases by nested PCR and qRT-PCR assays, respectively." (PMID 32424223, 2020). "Regarding underlying liver disease, 42.1% of TERT-mutated cases were associated with HCV infection, while no cases were linked to HBV." (PMID 40650279, 2025). "The expression of CD34 in sinusoidal endothelial cells was detected in two TERT mutation patients with non-cirrhotic portal hypertension, indicating an abnormal proportion of arterial blood flow to the sinuses." (PMID 39849589, 2025).
urothelial bladder cancer (11 papers, 2014 to 2026). "We aimed to validate the AbsoluteQ Digital PCR assay for the detection of urine-based TERT promoter variants for the diagnosis of urothelial bladder cancer and to assess its diagnostic performance in comparison with standard methods." (PMID 42087419, 2026). "TERT promoter mutations are often detected in precancerous UC lesions and high grade/stage urothelial bladder cancer, or in rare variant pathologies with an aggressive phenotype." (PMID 37598154, 2023). "Telomerase reverse transcriptase (TERT) promoter mutations occur in 60–80% of all urothelial bladder cancers (UBC) independent of tumor stage and grading thus, represent the most frequent alteration in this tumor entity." (PMID 33562516, 2021). "TERT amplifications have also important utility in diagnosis of a variety of solid tumours, including breast (differentiating phyllodes tumours from fibroadenomas), NSCLC and urothelial bladder carcinomas." (PMID 29751586, 2018).
Alzheimer disease (10 papers, 2018 to 2026). A progressive, neurodegenerative disease characterized by loss of function and death of nerve cells in several areas of the brain leading to loss of cognitive function such as memory and language. "The application of gene therapy to express active human TERT (hTERT) in human cells holds the potential to treat numerous neurodegenerative diseases associated with aging, including Alzheimer’s disease (AD)." (PMID 38203812, 2024). "We previously demonstrated that TERT protein can accumulate in mitochondria of Alzheimer’s disease (AD) brains and protect from pathological tau in primary mouse neurons." (PMID 33188884, 2021). "Our group found more TERT protein in mitochondria of hippocampal CA1 neurons of Braak 6 stage Alzheimer’s disease (AD) brains compared to brains from age-matched healthy controls." (PMID 33188884, 2021). "Additionally, TERT also prevents Tau‐mediated pathological damage by reducing ROS in animal model of Alzheimer's disease." (PMID 38421107, 2024). "Previous studies have demonstrated that TERT may protect against Alzheimer’s disease (AD) by lowering levels of reactive oxygen species (ROS) and preventing oxidative harm." (PMID 38315329, 2024). "Since Alzheimer’s disease occurs predominantly at higher age, one would expect that neuronal TERT protein levels might decrease during disease progression." (PMID 33946850, 2021). "TERT may activate autophagy for toxic neuronal proteins and ameliorate the effects of amyloid-β, pathological tau, and α-synuclein involved in neurodegenerative diseases such as Alzheimer’s disease and Parkinson’s disease." (PMID 35159976, 2022). "The mitochondrial dynamics and mitophagy are also impaired during thedevelopment of Alzheimer’s disease.This is evidenced by alterations in the expression of the ATG5, Beclin1, LC3A,LC3B, PINK1, TERT, BCL2, and BNIP3L genes detected in a mouse model of AD." (PMID 41479568, 2025).
astrocytic tumor (10 papers, 2015 to 2024). A glial tumor of the brain or spinal cord showing astrocytic differentiation. "Rare combinations of histology and molecular features including oligodendroma, histologically noted glioblastoma tumors with unknown IDH1/2 status, or IDH-WT high-grade astrocytic tumors with wild-type EGFR or TERT promoter mutations were excluded from the analysis." (PMID 39553337, 2024). "Merely to quote one couple of examples, most non-astrocytic tumors use TERT expression for telomere maintenance-mediated resistance, while HGG use the alternative lengthening of telomeres (ALT) pathway." (PMID 34445646, 2021). "Surprisingly, however, even IDH-mutant astrocytic tumors (DA/AA) without known hotspot mutations in the TERT promoter displayed certain amount of TERT immunoreactivity in their nuclei." (PMID 29693015, 2018). "Consistent with previous reports, oligodendroglial tumors (10 mutations out of 10 tumors: 100%) and IDH-wildtype GBM (7 mutations out of 11 tumors: 63.6%) possessed high incidence of TERT promoter mutations whereas no astrocytic tumors with IDH mutations showed them." (PMID 29693015, 2018). "On the other hand, several clearly astrocytic tumors (with purely astrocytic morphology, ATRX loss and lack of TERT promoter mutation) were identified as 1p/19q co-deleted using Natté’s criteria." (PMID 29923492, 2018).
bone marrow failure (10 papers, 2008 to 2025). "DKC is a usually a disease of childhood; bone marrow failure due to TERT mutations can affect individuals of a wide range of ages." (PMID 20502709, 2010). "Identification of the constellation of findings (liver abnormalities, cytopenias, premature graying of the hair) consistent with rare genetic mutations in TERT or TERC mutations is critical, as these patients are at risk for bone marrow failure and cryptogenic liver cirrhosis." (PMID 26400796, 2015).
cholangiocarcinoma (10 papers, 2016 to 2026). A carcinoma that arises from the intrahepatic biliary tree (intrahepatic cholangiocarcinoma) or from the junction, or adjacent to the junction, of the right and left hepatic ducts (hilar cholangiocarcinoma). "Taken together, the fact that TERT promoter mutations are detectable only in a small subset of cholangiocarcinoma indicates that the mechanism of telomerase activation is evidently different from telomerase activation in many HCCs." (PMID 32722302, 2020). "In contrast to frequent mutations in the TERT promoter region in HCC, TERT promoter mutations are less frequently analyzed in cholangiocarcinoma." (PMID 32722302, 2020). "We evaluated the frequency of TERT promoter and CTNNB1 mutations in 146 hepatocellular nodules including HCAs, LRNs, LDNs, HDNs, HCCs, and combined HCCs and cholangiocarcinomas." (PMID 27661004, 2016). "We have analyzed TERT promoter and CTNNB1 gene mutations in 122 cases of hepatitis B (HBV) and hepatitis C (HCV) related HCCs, in 7 cases of cholangiocarcinoma (CC) and hepatocholangiocarcinoma (HCC-CC) as well as in autologous cirrhotic tissues." (PMID 27276713, 2016).